APOE (apolipoprotein E)
Diseases named in the same sentence as APOE in open-access papers (continued):
Sharing a sentence is not in itself a finding about the gene and the disease.
meningioma (8 papers, 2014 to 2023). A generally slow growing tumor attached to the dura mater. "They demonstrated that APOE can be a potential tumor progression marker in meningioma based on the multiple reaction monitoring (MRM) tests utilizing CSF." (PMID 34966627, 2021). "For the meningioma CSF samples, three peptides of APOE (SELEEQLTPVAEETR, LGPLVEQGR and AATVGSLAGQPLQER) gave a cumulative fold change of 2.21 whereas peptides of PTGDS (WFSAGLASNSSWLR, TMLLQPAGSLGSYSYR and AQGFTEDTIVFLPQTDK) showed a fold change of 1.52." (PMID 34055594, 2021). "ROC curve analysis demonstrated apolipoprotein E and A-I and hemopexin as efficient predictors for meningiomas." (PMID 25413266, 2014). "Western blot analyses of three differentially expressed targets proteins; apolipoprotein E, ceruloplasmin and clusterin were carried out using a subset of healthy control and meningiomas samples (MGI, MGII and MGIII)." (PMID 25413266, 2014). "Some examples are the APOE and A-I, considered potential predictors for meningiomas." (PMID 32587372, 2020). "The results posed apolipoprotein E and A-I and hemopexin as potential predictors for meningiomas." (PMID 32587372, 2020). "In the current study, we have observed an upregulation of APOE and APOA1 in GBMs when compared to LGGs and upregulation of APOE and downregulation of APOA1 in Meningioma Grade II tissue compared to Meningioma Grade I." (PMID 34055594, 2021). "Hemopexin (HPX), apolipoprotein E and A-I (Apo E and A-I), and plasma retinol binding protein (RBP4) concentrations were directly measured in the serum samples of healthy controls and meningiomas patients (MGI, MGII and MGIII) using ELISA." (PMID 25413266, 2014). "Increased levels of lipids in serum of GBM patients and over expression of APOE in meningioma CSF sample in comparison to non-tumor CSF have also been reported and." (PMID 34055594, 2021).
pancreatic ductal adenocarcinoma (8 papers, 2022 to 2025). An infiltrating adenocarcinoma that arises from the epithelial cells of the pancreas. "Apolipoprotein E (APOE) is highly expressed in TAMs infiltrating pancreatic ductal adenocarcinoma (PDAC) compared to macrophages in adjacent tissues." (PMID 40270603, 2025). "In the case of pancreatic ductal adenocarcinoma (PDAC), increased levels of apolipoprotein E (APOE) have been associated with immune suppression, and higher serum APOE levels have been correlated with poorer patient survival." (PMID 38054821, 2023). "al. also showed that expression of ApoE was higher in peripheral monocytes of pancreatic ductal adenocarcinoma patients compared to healthy individuals, suggesting that elevated monocyte ApoE expression represents a systemic response to the tumor." (PMID 37623681, 2023). "Apolipoprotein E (ApoE) mediates the infiltration of TAMs in pancreatic ductal adenocarcinoma." (PMID 37569407, 2023). "Additionally, human APOE levels were elevated in pancreatic ductal adenocarcinoma and correlated with patient survival; notably, APOE-/- mice exhibited an increase in infiltrating CD8+ T cells." (PMID 36639681, 2023). "In pancreatic ductal adenocarcinoma (PDA) patients, elevated plasma APOE protein levels are associated with poor survival, whereas tumor associated macrophages that are key drivers of immunosuppression are characterized by elevated levels of ApoE in both mouse and human PDA." (PMID 36341364, 2022).
xanthoma (8 papers, 2012 to 2024). A non-neoplastic disorder characterized by a localized collection of histiocytes containing lipid. "In the brain of ApoE−/− mice, the deficiency of ApoE was associated with gliosis stimulation, microglia activation and xanthoma accumulation around blood vessels." (PMID 22709928, 2012). "For example, the genes which increased most in hubness in the two skin tissues were APOE, which has been linked with skin lesions known as xanthomas (although it is more famous because of its link with Alzheimer’s) and CERS3, which when mutated causes congenital ichthyosis, a skin disease." (PMID 25970446, 2015). "One subject with a pathogenic (p.Glu63ArgfsTer15) APOE variant and another subject with a likely pathogenic (rs121918393, APOE2 Heidelberg) APOE variant had xanthomas (tendon or cutaneous eruptive, respectively)." (PMID 37685967, 2023). "The APOE-deficient patient, aged 40 years, had severe xanthomas in various organs but normal neurocognitive and cardiac functions, which may suggest that the presence of APOE4 rather than the absence of APOE, may promote cognitive dysfunction." (PMID 38216055, 2024). "Both TNFSF12−/−ApoE−/− and anti-TWEAK-treated mice exhibited a reduced frequency of lateral xanthomas, medial erosion and presence of buried caps compared with TNFSF12+/+ApoE−/−." (PMID 24479820, 2014).
alcoholism (7 papers, 2015 to 2024).
aneurysmal disease (7 papers, 2011 to 2023). "Here, we used angiotensin II (AngII)-infused apolipoprotein E deficient mice to study the involvement of the PDE4 subfamily in aneurysmal disease." (PMID 33809405, 2021). "This suggests that Opg deficiency may have a preventive effect on AngII-induced aortic dilatation and dissection (43.75% in ApoE-/-Opg+/+ mice vs. 18.75% in ApoE-/-Opg-/- mice)." (PMID 32614927, 2020). "Treatment with CGA (400 mg/kg) or atorvastatin (4 mg/kg) for 12 weeks significantly reduced vascular wall thickness of the ascending aorta 2 cm above the aortic valve (AV, arrow) and at the origin of the brachiocephalic (BC) artery, suggesting that CGA inhibits aortic dilatation in ApoE−/− mice." (PMID 25187964, 2014). "Additional investigation in Apolipoprotein E (ApoE) –/– mice (deficient in NLRP3, caspase recruitment domains, and caspase-1) found reduced elastic lamina degradation and MMP activation in early AAA formation, further supporting a role for the NLRP3 inflammasome in aneurysmal disease." (PMID 38275364, 2023).
Aortic dissection (7 papers, 2018 to 2023). Aortic dissection refers to a tear in the intimal layer of the aorta causing a separation between the intima and the medial layers of the aorta. "Continuous infusion of angiotensin II (AngII) into apolipoprotein E-deficient mice induces the formation of aortic dissection and expansion at some point after implantation of miniosmotic pumps containing AngII." (PMID 31069328, 2018). "Therefore, we asked whether specific depletion of MCs could prevent the aneurysmal remodelling in ApoE-/- mice subjected to chronic infusion of Angiotensin II (AngII), a well-known mouse model of aortic dissection eventually followed by aneurysmal progression." (PMID 38055674, 2023). "Importantly, for reaching this conclusion, we used the ApoE-RMB mouse model in which the depletion of MCs, conditioned by the use of DT, started only after the initial trigger (aortic dissection)." (PMID 38055674, 2023).
cardiomyopathy (7 papers, 2020 to 2024). A disease of the heart muscle or myocardium proper. "The missing or dysfunctional apoE protein, such as apoE4, is always associated with increased intracellular cholesterol and lipid accumulation and accompanied by cardiomyopathy and cardiac diastolic dysfunction." (PMID 34575848, 2021). "However, a direct link between the apoE defects and development of cardiomyopathy is still under debate." (PMID 34816004, 2021). "We noted in that study that ApoE-/- mice on a WD exposed to nicotine e-cigarettes (2.4% nicotine) had decreased LV%FS, LVEF, and VCF coupled with LV ultrastructural abnormalities indicative of cardiomyopathy in comparison with e-cigarette (0% nicotine) or saline-aerosol exposed mice." (PMID 33002059, 2020).
Delusion (7 papers, 2012 to 2025). A delusion is a fixed false belief held despite evidence to the contrary. "Our observed association of APOE genetic variation with delusions and hallucination aligns with these prior findings." (PMID 39974048, 2025). "However, the underlying mechanism by which APOE affects the occurrence of hallucinations and delusions has yet to be elucidated." (PMID 23270420, 2012). "In general, these investigations were carried out on small samples of patients and neglected important potentially confounding factors such as, for example, the ApoE status of patients with and without delusions, since the ε4 allele is associated with increased risk of psychotic symptoms." (PMID 35554669, 2023).
endometriosis (7 papers, 2021 to 2025). The growth of functional endometrial tissue in anatomic sites outside the uterine body. "APOE was associated with 17 drugs for treating endometriosis, ICAM1 with 5 drugs, and MME with 8 drugs for treating endometriosis." (PMID 39650066, 2024). "Moreover, ApoE4 carriers (ρ3/ε4, ε4/ε4) differed significantly, and the ApoE-ε4 allele was found to be substantially associated with endometriosis." (PMID 39000283, 2024). "ApoE was not frequently associated with endometriosis, although some research tried to establish a connection between the two." (PMID 39000283, 2024). "The increased gene expression of apolipoprotein E (APOE), involved in the metabolism of lipids, has been noted in patients with endometriosis compared to healthy woman." (PMID 37558907, 2023). "Among the top 20 genes, APOE, DUSP1, MGST1, G0S2, ID4, WEE1, and H2AFZ expression levels were upregulated in the oocytes of patients with endometriosis." (PMID 33467661, 2021).
Headache (7 papers, 2015 to 2024). Cephalgia, or pain sensed in various parts of the head, not confined to the area of distribution of any nerve. "For acute pain, only APOE-ε2 carriers have an increased risk to develop headaches (OR = 1.35, p = 0.046)." (PMID 35149686, 2022). "In females, the association between APOE polymorphisms and pain was substantially weaker and found only for carriers of APOE-ε4 who have reduced risk to develop chronic back pain (OR = 0.45, p = 0.0007), and headaches (OR = 0.65, p = 0.0045)." (PMID 35149686, 2022). "Presumably, such alterations are not directly related to the central pain sensitization, rather to other aspects of chronic headache or the excessive intake of acute headache medications, e.g. the decrease of VDBP and APOE could indicate liver stress due to excessive medication intake." (PMID 31623575, 2019).
hemochromatosis (7 papers, 2006 to 2022). A disorder of iron metabolism characterized by a triad of HEMOSIDEROSIS; LIVER CIRRHOSIS; and DIABETES MELLITUS. "Examples are common apolipoprotein E, β-globin, and hemochromatosis polymorphisms." (PMID 16756678, 2006). "It is of interest that two of the tests mentioned by Dr. Weber as potentially included in the scan are hemochromatosis and apolipoprotein E (APOE) genotyping." (PMID 16756678, 2006). "In details, four genes of iron homeostasis (Hemochromatosis (HFE: C282Y, H63D), Ferroportin (FPN1: -8CG), Hepcidin (HAMP: -582AG), Transferrin (TF: P570S)), and the three major alleles of APOE (APOE2, APOE3, APOE4) were analyzed to explore causative interactions and synergies." (PMID 29518107, 2018).
lymph node metastasis (7 papers, 2013 to 2025). "However, complement C4b1 and apoE were markedly correlated with tumor TNM staging and lymph node metastasis." (PMID 23946775, 2013).
multiple system atrophy (7 papers, 2020 to 2024). Multiple system atrophy (MSA) is a neurodegenerative disorder characterized by autonomic failure (cardiovascular and/or urinary), parkinsonism, cerebellar impairment and corticospinal signs with a median survival of 6-9 years. "Moreover, APOE variants play a differential role in determining α-synucleinopathies, e.g., PD, Lewy bodies dementia, and multiple system atrophy (MSA)." (PMID 39596597, 2024).
obstructive sleep apnea (7 papers, 2020 to 2025). "We included many of these in our analyses to determine if the finding may be specific to REM sleep itself or to other contributing factors such as vascular health, obstructive sleep apnea, and ApoE status." (PMID 32645032, 2020).
peripheral vascular disease (7 papers, 2017 to 2023). Any disorder affecting blood flow through the veins or arteries outside of the heart. "On the basis of our results, we strongly believe that in the future APOE polymorphism needs to be included in complex genetic risk scores to assess cardiovascular risk, even in patients affected by advanced peripheral vascular disease." (PMID 37629219, 2023). "This study represents the prolonged follow-up to our first observational registry, which was conducted to investigate a possible relationship between APOE gene polymorphisms and more aggressive forms of atherosclerotic disease among subjects with peripheral vascular disease." (PMID 37629219, 2023). "We found that APOE, IGF1R, HMGCR, APOA1, ENG, SERPINA3 and LCN2 were hub proteins in the network, which were also predicted to be associated with peripheral vascular disease." (PMID 37496672, 2023).
renal cell carcinoma (7 papers, 2018 to 2025). "This is in keeping with findings from other malignancies, such as renal cell carcinoma, where APOE-enriched M2-like TAMs have been associated with disease progression." (PMID 40432828, 2025). "Interestingly, C1q genes and APOE were included in a TLS signature of renal cell cancer associated with better ICB response, indicating a potential role of C1QC+ macrophages in helping to eliminate tumor cells in ICB therapy." (PMID 37492578, 2023). "A functional region of APOE could increase renal cell carcinoma susceptibility in a two stage case-control study." (PMID 30466390, 2018). "ApoE-/- upregulated IL-6, Renal cell carcinoma, PRRs in recognition of bacteria and viruses, VDR/RXR activation, Phenylalanine degradation IV pathways in Ly6Chigh MC." (PMID 34987524, 2021).
renal failure (7 papers, 2013 to 2023). "Consistent with the transcriptomic data of a study on young and aged human kidneys we found apolipoprotein E and Fabp1, a potential marker of acute kidney injury, to be increased in aged kidney samples pointing to a conserved aging mechanism." (PMID 26886165, 2016). "There are several reported cases with APOE but asymptomatic for LPG or renal failure." (PMID 35756922, 2022). "We could suppose that ε3 homozygotes with more advanced kidney failure accumulated IDL + LDL particles in the plasma since an increase in APOB-(IDL + LDL) concentration with a decline of eGFR has been observed and the ratio of APOE/APOB in IDL + LDL remained constant." (PMID 30851738, 2019).
spinal cord injury (7 papers, 2018 to 2025). Penetrating and non-penetrating injuries to the spinal cord resulting from traumatic external forces (e.g., WOUNDS, GUNSHOT; WHIPLASH INJURIES; etc.). "Previous studies have shown that APOE4 is associated with poorer neurological recovery and longer rehabilitation time in patients with traumatic cervical spinal cord injury, s suggesting a potential role for ApoE in spinal cord injury." (PMID 38545108, 2024).
adenoma (6 papers, 2014 to 2023). A neoplasm arising from the epithelium. "The univariable analyses performed on a well-characterized cohort (the Swedish Watchful Waiting Cohort after TURP or adenoma enucleation), revealed a positive association of increased expression of APOE, YWHAZ, and NDRG1 with poor OS." (PMID 33483585, 2021). "Through association studies, ApoE was suggested to play a role in colon homoeostasis and cancer with polymorphisms in the ApoE alleles constituting a risk factor for the development of adenoma and carcinoma of the colon." (PMID 27538678, 2016). "However, in patients with the ε4 allele of APOE, the levels of biliary deoxycholic acid are relatively low, which may be associated with the low incidence of adenoma and carcinoma." (PMID 25029444, 2014). "The average number of adenomas was 17.6 ± 4.0 in WT mice, but only 3.3 ± 0.5 in ApoE KO mice." (PMID 31275318, 2019). "APOE seems to be involved in immunoregulation and inhibiting endothelial cell proliferation, which may directly affect the adenoma to carcinoma process." (PMID 25029444, 2014). "Yet these findings still need further investigation, as another study involving Japanese males could not identify these correlations between APOE-ε4 and proximal adenomas, suggesting that APOE is affected by other factors other than genes, for example, ethnicity in this case." (PMID 38067270, 2023).
aging (6 papers, 2017 to 2026). A developmental process that is a deterioration and loss of function over time. "Larger samples with greater power to detect smaller effects are needed to further evaluate the role of the APOE ε4 allele in healthy cognitive aging." (PMID 38524117, 2024). "Over the next decades, APOE personalized strategies will better guide our approach in reclassifying and targeted managing of APOE4-associated aging diseases." (PMID 32587511, 2020). "Associated with aging diseases, such as heart disease, AD, which share certain traits, are common in etiopathogenesis and AMD, APOE association with AMD, and then investigated." (PMID 40625502, 2025).
alcohol abuse (6 papers, 2013 to 2025). The use of alcoholic beverages to excess, either on individual occasions ("binge drinking") or as a regular practice. "Other significant factors that emerged included presence or history of CAD, currently smoking, alcohol abuse, being overweight, Asian race, and Hispanic ethnicity (levels of education and APOE status were not significant factors)." (PMID 37580727, 2023).
clear cell renal carcinoma (6 papers, 2022 to 2025). A malignant epithelial neoplasm of the kidney characterized by the presence of lipid-containing clear cells within a vascular network. "In clear cell renal cell carcinoma, the existence of C1Q+APOE+ macrophages is associated with tired T cells, creating an impaired immune system in the form of a malfunctioning circuit." (PMID 39187937, 2024). "TREM2+ macrophages have been found to accumulate in human tumors, with infiltration of TREM2/APOE/C1Q expressing macrophages serving as a potential biomarker for disease recurrence in clear cell renal carcinoma." (PMID 39811671, 2025).
coronary stenosis (6 papers, 2011 to 2025). Narrowing of the coronary artery lumen diameter. "A study indicated an association between the CELSR2 T/T risk genotype, elevated ApoE and ApoB levels, and coronary artery stenosis extension." (PMID 40076958, 2025). "Despite this limitation, we have previously reported a significant association of APOE with coronary stenosis in our sample which has been confirmed by another study that also used an angiography-assessed small sample." (PMID 32685059, 2020). "This study aimed to assess the association between APOE polymorphism and angiographically assessed coronary stenosis in Pakistani population." (PMID 25883965, 2015). "Group differences in heart weight remained significant after adjustment for age, gender, body mass index and apolipoprotein E genotype while differences in coronary artery stenosis were significantly associated with body mass index alone." (PMID 21266042, 2011). "Similar to the whole cohort, subjects in the low ApoE-HDL-C group had more coronary artery stenosis classified by CAD-RADS as 4A (severe stenosis) and 5 (total occlusion) as compared with the high ApoE-HDL-C group (overall P = 0.01)." (PMID 35389891, 2022). "The aim of our study was to seek the association between APOE polymorphism and angiographically assessed coronary stenosis among Pakistanis, which to the best of our knowledge has not been reported previously." (PMID 25883965, 2015). "Carriage of the Apolipoprotein E-ε4 allele did not influence the degree of coronary stenosis." (PMID 21266042, 2011). "Our analysis shows a clinically worse cardiometabolic profile, more significant coronary artery stenosis, and higher CAC scores in patients with low ApoE-HDL-C as compared with the high ApoE-HDL-C group." (PMID 35389891, 2022).